TRIM63 (tripartite motif containing 63)
Diseases named in the same sentence as TRIM63 in open-access papers (continued):
Sharing a sentence is not in itself a finding about the gene and the disease.
Sepsis (30 papers, 2008 to 2026). Sepsis is defined as life-threatening organ dysfunction caused by a dysregulated host response to infection. "In young survivors, cardiac Foxo1 and its downstream effector Trim63 (MuRF1) protected from sepsis-induced cardiac remodelling, multi-organ injury and mortality." (PMID 41535469, 2026). "Fbxo30, Fbxo32, and Trim63 expression was increased in both muscles of septic mice, compared with sham controls, indicating that sepsis leads to an activation of the atrophy program in muscle." (PMID 31441598, 2020). "The Atrogin1/Fbxo32 and MuRF1/Trim63 protein content increased during sepsis in tibialis anterior and BMS‐345541 attenuated this response." (PMID 31441598, 2020). "In order to investigate if the atrophy program is activated in skeletal muscle during sepsis, we quantitated the expression of Fbxo30, Fbxo32, and Trim63 in both muscles of sham and CLP mice." (PMID 31441598, 2020). "Accordingly, sepsis‐induced reduction in Myh4 expression and induction of Trim63/MuRF1 and Fbxo32/Atrogin1 expression was reversed by BMS‐345541." (PMID 31441598, 2020). "Ubiquitin-proteasome system markers Fbxo32 and Trim63 mRNA were also comparably affected by sepsis in both groups of lean mice." (PMID 31262340, 2019). "In another study, PGC1β mRNA expression in mice and rats was found to be decreased in response to sepsis and dexamethasone, where both conditions induce ubiquitin mediated proteolysis through up-regulation of Fbxo32 and Trim63 expression." (PMID 28860475, 2017). "Conversely, in aged hosts, Foxo1 and Trim63 acted as drivers of sepsis pathogenesis and death." (PMID 41535469, 2026). "However, the sepsis‐induced upregulation of atrophy markers (Fbxo32, Trim63, Ubc, Ubb) was further increased in the Low‐LCT and High‐LCT groups, while expression of myostatin (Mstn) was higher only in the Low‐LCT group." (PMID 41365288, 2025). "Besides the atrophy markers Trim63/MuRF1, Fbxo32/Atrogin‐1, and Fbxo30/MuSA1 (all induced >5‐fold by sepsis, P < 0.001) the expression of Spsb1 was significantly increased after 24 and 96 h of sepsis (24 h: 20‐fold; 96 h: 34‐fold, P < 0.001)." (PMID 37209006, 2023). "Spsb1 knockdown attenuated sepsis‐induced increases in Trim63 and Fbxo32 expression." (PMID 37209006, 2023). "Fbxo32 and Trim63 levels increased in the TA after 24, 48, and 96 h of sepsis." (PMID 31660704, 2019). "Fbxo32 (atrogin‐1) and Trim63 (MuRF1) mRNA levels increased in the DIA after 24 and 96 h of sepsis." (PMID 31660704, 2019).
hypertrophic cardiomyopathy (15 papers, 2011 to 2025). "For instance, mutated TRIM32 leads to limb-girdle muscular dystrophy type 2H; mutations in TRIM18 (MID1) cause Opitz G/BBB syndrome; and TRIM63/MuRF1 mutations result in hypertrophic cardiomyopathy." (PMID 25263070, 2014). "Among hypertrophic cardiomyopathy (HCM) patients, 24 TRIM63 variants have been identified, with 1 additional variant linked to restrictive cardiomyopathy." (PMID 40332812, 2025). "In addition, it has been shown that a homozygous TRIM63/MuRF1 null mutation in combination with the heterozygous TRIM54/MuRF3 mutation leads to a myosin storage myopathy associated with skeletal muscle hypertrophy and hypertrophic cardiomyopathy in patients." (PMID 34572540, 2021).
heart failure (14 papers, 2011 to 2025). Inability of the heart to pump blood at an adequate rate to meet tissue metabolic requirements. "TRIM63 (MuRF1) overexpression induced thinning of the left ventricular wall and deterioration of cardiac function, ultimately leading to heart failure." (PMID 32343488, 2020).
Insulin resistance (13 papers, 2012 to 2025). Increased resistance towards insulin, that is, diminished effectiveness of insulin in reducing blood glucose levels. "Increased expression of the E3 ubiquitin ligases Atrogin‐1/FBX032 and TRIM63/MuRF‐1 were measured following injury, as was skeletal muscle insulin resistance, as evidenced by decreased insulin‐inducible insulin receptor (IR) and AKT/PKB (Protein Kinase B) phosphorylation." (PMID 26818585, 2016).
melanoma (11 papers, 2013 to 2025). A malignant, usually aggressive tumor composed of atypical, neoplastic melanocytes. "In conclusion, this study significantly enhances our understanding of the molecular mechanisms underlying BRAF-driven melanoma progression by elucidating the TRIM63/IRF-8 axis." (PMID 41315179, 2025). "Clinically, the presence of pS69 on TRIM63 is associated with tumor immunosuppression and poor prognosis among melanoma patients, highlighting its potential as a promising therapeutic target." (PMID 41315179, 2025). "Here, we observe that TRIM63 is another oncogenic TRIM protein in melanoma progression, highly associated with poor prognosis of patients." (PMID 41315179, 2025). "At least one of these genes, TRIM63, is known to be strongly associated with melanoma, and is a validated target of MITF, the primary transcription factor controlling expression of pigmentation genes." (PMID 39294560, 2024). "The underlying mechanisms of TRIM63 in melanoma are still uncharted." (PMID 41315179, 2025). "Lastly, TRIM63 was implicated in melanoma cell migration/invasion." (PMID 33564068, 2021). "Intriguingly, we observed significantly elevated expression levels of TRIM63 with strong clinical correlations in melanoma patients." (PMID 41315179, 2025). "Consistently, treatment with the MAPK inhibitor U0126 abolished the interaction between ERK and TRIM63, and inhibited TRIM63 phosphorylation in melanoma cells carrying BRAF V600E." (PMID 41315179, 2025). "In this study, we demonstrate that TRIM63 exhibits overexpression in melanoma cells and exerts its full oncogenic potential upon activation of the MAPK signaling pathway." (PMID 41315179, 2025). "The protein levels of TRIM63 from our clinical samples were also higher in melanoma than in normal skin tissues." (PMID 41315179, 2025). "Collectively, the data indicated that TRIM63 interacts with ERK1/2 and undergoes phosphorylation by ERK1/2 within melanoma cells harboring BRAF mutations." (PMID 41315179, 2025). "Further analysis indicated that high expression of TRIM63 represented a worse prognosis of melanoma patients." (PMID 41315179, 2025). "Similar outcomes were also observed from other datasets (GSE19234, GSE15605), which suggested the generality of high TRIM63 expression in melanoma." (PMID 41315179, 2025). "In conclusion, these results suggested that the regulatory axis of TRIM63 pS69/IRF-8 plays a critical role in clinical outcomes of human melanoma." (PMID 41315179, 2025). "Our results demonstrated that TRIM63 pS69 was barely detectable in normal skin samples, whereas it was significantly overexpressed in melanoma samples." (PMID 41315179, 2025). "The E3 ligase TRIM63 demonstrates a robust correlation with melanoma malignancy, particularly in cases involving BRAF mutants." (PMID 41315179, 2025). "Herein, we identify that TRIM63-mediated degradation of IRF-8 provides a mechanistic explanation for observed immune evasion in numerous melanoma cases." (PMID 41315179, 2025). "As anticipated, we observed that TRIM63 is significantly phosphorylated in melanoma cells with BRAF V600E compared to those with wild-type BRAF, while the expression levels remained comparable." (PMID 41315179, 2025). "This study identifies a novel oncogene, TRIM63, and elucidates its functional mechanisms that drive melanoma progression associated with BRAF mutations commonly observed in melanoma." (PMID 41315179, 2025). "When both IRF8 and TRIM63 were simultaneously knocked down, the cell proliferation abilities were partially restored, suggesting that the TRIM63/IRF8 axis plays a critical role in promoting melanoma cell proliferation." (PMID 41315179, 2025). "The produced decision tree consists of three informative genes (KLK8, TIGIT, and TRIM63) along with a threshold level for each gene, which together provide a simple method for classifying melanoma tumors into one of the four subgroups." (PMID 33564068, 2021).
melanoma (continued). "A comprehensive understanding of the functional and mechanistic dynamics of TRIM63 may unveil potential therapeutic targets for melanoma treatment." (PMID 41315179, 2025). "Considering TRIM63-dysfunction in melanoma cells carrying BRAF mutant, we speculated that TRIM63 may be associated with BRAF mutation." (PMID 41315179, 2025). "Notably, high levels of TRIM63 pS69 were correlated with decreased overall durations of survival in melanoma patients." (PMID 41315179, 2025). "This highlights an “uncultivated land” of TRIM63 in melanoma that warrants further investigation." (PMID 41315179, 2025). "Notably, after TRIM63 depletion, the oncogenic effect of TRIM63 exhibited significant alterations exclusively in melanoma cells harboring BRAF mutations, while no such changes were observed in cells without BRAF mutation." (PMID 41315179, 2025). "Furthermore, in vivo studies demonstrated that TRIM63 overexpression exerted effects solely on melanoma cells with BRAF mutations rather than those with wild-type BRAF." (PMID 41315179, 2025). "To investigate the mechanism, we primarily detect that protein stability of IRF-8 in BRAF V600E melanoma cells, indicating that cycloheximide treatment significantly decreased IRF-8 protein levels, partially restored by TRIM63 deletion." (PMID 41315179, 2025). "Subsequently, the interaction between TRIM63 and activated ERK1/2 was investigated in melanoma cells." (PMID 41315179, 2025). "In melanoma, KLK8, TIGIT, and TRIM63 were identified as the representative three-gene classifier for melanoma molecular subtypes to predict patients’ survival risk." (PMID 38273291, 2024). "Average TRIM63 RNA-ISH H-scores for PEComa, melanoma, and granular cell tumor were generally lower than staining observed in ASPS (p = 0.06 for PEComa, p < 0.0001 for melanoma, and p = 0.0005 for granular cell tumor)." (PMID 38393424, 2024). "TRIM63 was already identified as a MITF target and was reported to be involved in melanoma cell migration and invasion." (PMID 33462405, 2021). "To evaluate the clinical significance of TRIM63 pS69, we performed immunohistochemical staining on both normal human skin and melanoma tissues using an anti-TRIM63 pS69 antibody." (PMID 41315179, 2025). "Similarly, in melanoma, TRIM63 and CAPN3 are a direct target of MiTF, wherein TRIM63 mRNA expression was positively correlated with MiTF transcription factor and knockdown of MiTF decreased TRIM63 levels." (PMID 38393424, 2024). "Subsequently, to investigate the impact of TRIM63 on IRF-8, we conducted TRIM63 depletion, which resulted in an increase in IRF-8 protein levels specifically in melanoma cells harboring BRAF V600E mutation, while no such effect was observed in cells with wild-type BRAF." (PMID 41315179, 2025). "In our cohort, while tumors that have MiTF pathway activation without TFE3 rearrangement (i.e., granular cell tumor and melanoma) demonstrated TRIM63 RNA hybridization, they generally did so at a lower level than that of ASPS, with lower average H-scores (p < 0.05)." (PMID 38393424, 2024).
chronic kidney disease (8 papers, 2014 to 2022). Impairment of the renal function secondary to chronic kidney damage persisting for three or more months. "Although the miR-27a-–FoxO1 interaction is not validated in skeletal muscle cells, the overexpression of miR-27a in mice with chronic kidney disease attenuated muscle loss, improved grip strength, and decreased the expression of FoxO1, Trim63, and Fbxo32 proteins." (PMID 31013615, 2019).
cardiomyopathies (6 papers, 2020 to 2025). "Eight (11.59%) hits concerned substrate defects, such as fibro-adipose substitution or RV end-diastolic volume (EDV), and they mainly involved genes associated with cardiomyopathies and muscle dysfunction, including TRIM63, MYH6, SGCD and LAMA2." (PMID 36008935, 2022). "Furthermore, systolic dysfunction and late gadolinium enhancement have been reported as characteristic features of TRIM63-associated cardiomyopathies." (PMID 39554508, 2024). "The development of cardiomyopathy and skeletal myopathy associated with subsarcolemmal myosin accumulation and non-ubiquinated aggregates of fragmented sarcomeres were observed in a patient with compound MuRF1 (TRIM63) deficiency and a deleterious MuRF3 (TRIM54) missense mutation." (PMID 33234710, 2020).
chronic heart failure (6 papers, 2009 to 2022). "MuRF- (TRIM63-) mRNA expression was found to be increased in the sarcopenic vastus lateralis muscle of patients with chronic heart failure." (PMID 34648569, 2021).
pancreatic cancer (6 papers, 2021 to 2025). "Integrated in vivo proteome, ubiquitinome, and metabolome profiling characterizes the crucial role played by the E3 ubiquitin ligase MuRF1/Trim63 in the cross-talk between muscle wasting and pancreatic tumor growth." (PMID 37179425, 2023).
colorectal cancer (4 papers, 2016 to 2025). A primary or metastatic malignant neoplasm that affects the colon or rectum. "More importantly, we identified genes (e.g., Trim63, Fos, Col1a1, and Six2) that were regulated by high-intensity aerobic exercise, which adversely affected colorectal cancer development, and confirmed their effects in vitro using knockdown and overexpression systems." (PMID 35801156, 2022).
Hyperinsulinemia (4 papers, 2011 to 2023). An increased concentration of insulin in the blood. "Muscle atrogenes such as MuRF1/Trim63 and Atrogin1/Fbxo32 were downregulated in ob/ob GRfl/fl mice compared with lean GRfl/fl mice, possibly reflecting the counteracting role of hyperinsulinemia in ob/ob mice for maintaining muscle mass." (PMID 36917179, 2023). "Transgenic mice overexpressing TRIM63 did not present with muscle atrophy but had hyperinsulinemia and reduced hepatic glycogen stores." (PMID 29454501, 2019).
lung carcinoma (4 papers, 2017 to 2025). "Also, TRIM63 is a key regulator in many other types of cancer, such as lung cancer, breast cancer, and kidney cancer." (PMID 41315179, 2025).
Stroke (4 papers, 2020 to 2021). Sudden impairment of blood flow to a part of the brain due to occlusion or rupture of an artery to the brain. "Our initial qPCR findings indicated both Atrogin-1 (Fbxo-32) and MuRF1 (Trim63) to be significantly upregulated in response to stroke." (PMID 32629989, 2020).
breast carcinoma (3 papers, 2022 to 2025). "In addition to Trim63, our results on Fos are also consistent with previous reports, where the inhibition of Fos suppressed colon carcinoma tumor growth in athymic mice as well as the progression of ovarian and breast cancer." (PMID 35801156, 2022).
glioma (3 papers, 2019 to 2023). A benign or malignant brain and spinal cord tumor that arises from glial cells (astrocytes, oligodendrocytes, ependymal cells). "Although there was no significant change in muscle weight was found, the expression of E3 ligases Trim63 and Fbxo32 was increased in the muscle of mice bearing IDH1 mutant glioma tumors, whereas it was attenuated after ivosidenib treatment." (PMID 37741882, 2023).
Hypertension (3 papers, 2015 to 2025). The presence of chronic increased pressure in the systemic arterial system. "However, we cannot exclude a modifying contribution of heterozygous missense TRIM63 variants in patients with poorly controlled hypertension, as in our case." (PMID 41440877, 2025).
Skeletal myopathy (3 papers, 2020 to 2024). "At least 2 reports include co-occurring HCM and skeletal myopathy in the presence of biallelic TRIM63 variants, though more evidence is needed to understand whether this should be considered part of an expanded phenotypic spectrum." (PMID 39132495, 2024). "The detected TRIM63 variant has been described in two literature reports in association with HCM and skeletal myopathy, but no OMIM phenotype had been assigned to the gene at the time of the genetic testing." (PMID 32659924, 2020).
atrial fibrillation (2 papers, 2021 to 2023). A disorder characterized by an electrocardiographic finding of a supraventricular arrhythmia characterized by the replacement of consistent P waves by rapid oscillations or fibrillatory waves that vary in size, shape and timing and are accompanied by an irregular ventricular response. "Novel variants in DCTN1, MYH14, and RBM20 were identified in Family 1 with cardiac and limb-girdle muscle involvement and in TRIM63, ACTC1, and TTN in the proband of family 2 with a distal lower limb phenotype and atrial fibrillation." (PMID 33170376, 2021).
coronary heart disease (2 papers, 2015 to 2019). "We examined the plasma Rnf207, Fbxo32, Trim54, Trim63, Kbtbd10 and Asb11 in three groups (the AMI, coronary heart disease (CHD) and healthy groups)." (PMID 25599194, 2015).
COVID-19 (2 papers, 2021 to 2024). A disease caused by infection with severe acute respiratory syndrome coronavirus 2. "In the discovery cohort, anti-TRIM63 IgG prevalence was increased in hospitalized COVID-19 patients." (PMID 39414823, 2024). "Taken together, there is evidence suggestive of molecular mimicry between the immunologically important Spike protein fusion peptide and the muscle proteins TRIM63 and CCDC63 alongside associations with muscular symptoms post-COVID-19 and COVID-19 severity." (PMID 39414823, 2024). "According to our results, alterations in body composition are fundamental in the prognosis of COVID-19, since our study shows that muscle catabolism markers such as TRIM63 predict disease severity." (PMID 34566957, 2021). "The explanatory variables for COVID-19 severity were the body mass index (BMI), hemoglobin, albumin, 3-Hydroxyisovaleric acid, CD8+ effector memory T cells, Th1 cells, low-density granulocytes, monocyte chemoattractant protein-1, plasma TRIM63, and circulating neutrophil extracellular traps." (PMID 34566957, 2021).
ischemic stroke (2 papers, 2020 to 2022). A stroke disorder caused by obstruction of blood flow to the brain, due to thrombotic (local blood clot formation) or embolic (due to a blood clot or other material traveling from another site) event. "Previously, it has been shown that ischemic-stroke-induced skeletal muscle atrophy occurs in tandem with the upregulation of various genes related to the ubiquitin–ligase pathway, such as Atrogin-1 (Fbxo32) and MuRF1 (Trim63)." (PMID 32629989, 2020).
prostate carcinoma (2 papers, 2024 to 2025). A carcinoma that arises from epithelial cells of the prostate gland. "We find that gene expression of several androgen receptor (AR) target genes, including TRIM63, are inversely associated with DNA methylation only in prostate cancer from AA men." (PMID 38566104, 2024). "In prostate cancer from AA men, genes including known AR target genes TRIM63, ATP2A1, and ARHGAP28, showed a significant inverse correlation between gene expression and DNA methylation." (PMID 38566104, 2024).
Arrhythmia (1 paper, 2024). Any cardiac rhythm other than the normal sinus rhythm. "TRIM63 variant carriers showed concentric LV hypertrophy, significant cardiac fibrosis, LV systolic dysfunction, and arrhythmias." (PMID 39554508, 2024).
Danon disease (1 paper, 2025). A lysosomal glycogen storage disease characterized by severe cardiomyopathy and variable degrees of muscle weakness, frequently associated with intellectual deficit. "The dilated phenotype subgroup (P.1–P.10) included all patients with Danon disease, the patient with a homozygous ALPK3 variant, carriers of in-frame deletions in TTN and FLNC, a heterozygous TRIM63 missense variant, and carriers of splice-site variants in MYH7 and MYBPC3." (PMID 41440877, 2025).